MMP14 (matrix metallopeptidase 14)
Diseases named in the same sentence as MMP14 in open-access papers (continued):
Sharing a sentence is not in itself a finding about the gene and the disease.
melanoma (continued). "In order to validate the in silico data, MMP-14 activity and migration assays were performed using murine B16F1 and human HT-144 melanoma cells." (PMID 34638415, 2021). "In contrast to the HT-144 melanoma cell line, L9Mc significantly inhibited the migration of B16F1 cells and the activity of MMP-14 but with less efficacy than lumican and lumcorin." (PMID 34638415, 2021). "It is worth noticing that lumican downregulates the MMP-14 gene expression in both Mock-B16F1 and Snail-B16F1 melanoma cells." (PMID 33917849, 2021). "Correlating with a direct function of MMP14 on collagen XIV processing, peritumoral areas of melanoma displayed a high expression of MMP14 compared to stromal areas around the melanocytic nests of nevi." (PMID 34830157, 2021). "TIMPs can also form non-inhibitory pro-MMP/TIMP/MT-MMP complexes, as in the instance of TIMP-2 complexing with MMP-14 and which can activate pro-MMP-2 in human fibrosarcoma, breast, and melanoma cell lines." (PMID 33352765, 2020). "Lumcorin and L9M peptides, which contain the same LRR9 core sequence as L9Mc, have been described to inhibit melanoma cell migration in a mechanism including focal adhesion kinase (FAK) dephosphorylation and matrix metalloproteinase-14 (MMP-14) inhibition." (PMID 32548117, 2020). "The aim of this work was to investigate lumican effects on MMP-14 activity and migration of Snail overexpressing B16F1 (Snail-B16F1) melanoma cells and HT-29 colon adenocarcinoma cells." (PMID 26930497, 2016). "In MDA-MB-435 melanoma cells, TGF-β-induced upregulation of MMP14 has been shown to be dependent on the ERK1/2, PI3K, and JNK pathways and in MDA-MB-231 cells TGF-β induced the expression of many MMPs, including MMP14, through the p38 MAP kinase." (PMID 24053318, 2013). "In melanomas, higher levels of MMP-1, MMP-2, MMP-9, and MMP-14 have been observed in the more invasive and metastatic tumors." (PMID 20843370, 2010). "By targeting MMP9, MMP12, MMP14, and MMP16, it is conceivable that Estradiol and Calcitriol could disrupt critical pathways involved in melanoma progression, offering a novel and potentially effective approach for combating this aggressive form of skin cancer." (PMID 39493455, 2024). "In accordance with these observations and the negative impact of collagen XIV in melanoma formation, MMP14 expression was established as low in benign lesions with a tendency to increase with the advancement of melanoma." (PMID 39769318, 2024). "Several of the EMT-related genes with higher expression in NR patients encoded for molecules controlling adhesion (ITGB3, VCAM1, collagens, and others), interaction with extracellular matrix (VEGFA, MMP14, WNT5A, LAMA1, and others), and melanoma de-differentiation (KRT9, KRT10, EGFR, and others)." (PMID 37739939, 2023). "Using in vitro invasion systems devoid of cellular activities, we determined that the structural peritumoral environment generated in the absence of MMP14 in fibroblasts has an inhibitory effect on the growth of melanomas." (PMID 33924099, 2021). "MC38 (colon cancer), B16 (melanoma), and LLC (lung cancer) all expressed high MMP-14." (PMID 34620867, 2021). "Mice lacking MMP14 in stromal fibroblasts (MMP14Sf−/−) display skin fibrosis and reduced melanoma growth due to enhanced collagen I accumulation and increased skin stiffness." (PMID 34830157, 2021). "L9Mc significantly inhibited the migration of murine B16F1 but not human HT-144 melanoma cells and the activity of MMP-14 but with less efficacy than lumican and lumcorin." (PMID 34638415, 2021). "Indeed, lumican inhibits the degradation of ECM by inhibiting MMP-14, then influencing integrin clustering, modulating focal adhesion site stability and FAK phosphorylation at Tyr-397, leading to the inhibition of melanoma cell migration." (PMID 34572532, 2021). "Moreover, we identified collagen XIV as a substrate for MMP14, showing that enhanced collagen XIV correlates with reduced melanoma growth in mice." (PMID 34830157, 2021).
melanoma (continued). "This fact was not surprising, as melanoma cells can express MMP14 and navigate small paths generated in the ECM." (PMID 33924099, 2021). "Using atomic force microscopy, we found increased peritumoral matrix stiffness of early but not late melanomas in the absence of fibroblast-derived MMP14." (PMID 33924099, 2021). "A lack of MMP14 expression in fibroblasts would dramatically reduce proteolysis in peritumoral areas and affect melanoma outgrowth." (PMID 33924099, 2021). "Melanoma associated fibroblast are also able to remodel the ECM by MMP-1, MMP-2, MMP-13, and MT1-MMP (MMP-14) secretion, which could influence the motility and invasiveness of melanoma cells." (PMID 32984031, 2020). "We found that the interaction of melanoma cells with LECs induced matrix-metalloproteinase-14 (MMP14, also known as MT1-MMP) -dependent Notch3 and β1-integrin activation in the expansively growing metastatic melanoma cells, leading to invasive sprouting of cells in 3D matrices." (PMID 29712618, 2018). "Recent studies based on mRNA and protein expression show that several MMPs, namely MMP-9, MMP-12 MMP-2, MMP-14, and MMP-19, play a role in melanoma aggressiveness and consequently may represent useful prognostic biomarkers." (PMID 30591049, 2018). "MMP‐14 and its downstream effector MMP‐2 are major players in angiogenesis and tumorigenesis, and MMP‐13 promoted tumor angiogenesis, melanoma invasion, and metastasis." (PMID 27932444, 2017). "We further investigated whether MMP14 and Snail expression could be influenced by MALAT1 in melanoma cells." (PMID 27564100, 2016). "In addition to angiogenesis, under hypoxic conditions, HIF-1α plays an important role in the metastatic progression of melanoma by enhancing the expression of MMP such as MMP-2, MMP-9, and MMP-14." (PMID 27271600, 2016). "Subsequently, we demonstrated that MMP14 and Snail were the downstream target of MALAT1 ceRNA function and were important for MALAT1 to regulate melanoma cell phenotypes, suggesting that MALAT1 affected melanoma progression in a miR-22 site-dependent manner." (PMID 27564100, 2016). "In addition, we have previously shown that direct contact of melanoma cells with LECs strongly augments melanoma invasion and metastasis through induction of Notch3 in the melanoma cells that is dependent on matrix metalloproteinase 14 (MMP14, also known as MT1-MMP)." (PMID 37971882, 2024). "Apart from its degradative activity, it is possible to speculate, although no studies support this, that MMP14 proteolytic activity generates collagen XIV bioactive fragments supportive for melanoma growth." (PMID 34830157, 2021). "The MMP-14-Notch3-β1-integrin axis can be activated by interactions between lymphatic endothelial cells and melanoma cells, leading to the transformation of non-metastatic melanoma cells into invasively sprouting melanoma cells." (PMID 34195229, 2021). "In addition to MMP-2, CAFs secrete other proteolytic enzymes, including MMP-1, MMP-13, and MMP-14, which sustain melanoma invasion by leading to ECM digestion and formation of “tracks”, that melanoma cells use to move through the tumor mass and eventually leave the primary site." (PMID 34067929, 2021). "Similar to Bowes, LEC priming did not markedly alter the 3D phenotype of another non-metastatic melanoma cell line WM793, that, despite of MMP14 expression, continued to grow expansively in 3D as indicated by the sphere-like growth in 3D fibrin." (PMID 29712618, 2018).
melanoma (continued). "Due to that, we observed lower standard deviation and, thus, statistically significant differences in the level of MMP2, MMP14, RUNX2, or CD44 in CAFs obtained by incubation with conditioned media, but not by co-culturing with melanoma cells present on Transwell inserts." (PMID 35538545, 2022).
gastric cancer (65 papers, 2002 to 2025). A primary or metastatic malignant neoplasm involving the stomach. "Previous studies have shown that high expression of MMP14 is associated with poor prognosis of gastric cancer, colorectal cancer, and liver cancer." (PMID 34604053, 2021). "In previous studies, a high immunohistochemical MMP-14 expression in tissue samples associated with increased metastasis and a worse prognosis in gastric cancer." (PMID 30532247, 2018). "To further understand this association, we investigated serum MMP-14 as a biomarker in gastric cancer patients." (PMID 30532247, 2018). "A high matrix metalloproteinase-14 (MMP-14) expression in gastric cancer tissue has been associated with metastasis and poor prognosis." (PMID 30532247, 2018). "Studies showed that MMP-14 is elevated in gastric cancer patients, and overexpression of MMP-14 is closely associated with gastric cancer invasion." (PMID 29358963, 2017). "Dual-luciferase assay indicated that ectopic expression or knockdown of MZF1 enhanced and attenuated the promoter activity of MMP-14 in gastric cancer cells, respectively, and mutation of MZF1 binding site abolished these effects." (PMID 27259238, 2016). "It has been indicated that miR-337-3p is under-expressed and associated with the lymph node metastasis of gastric cancer, and is able to directly bind to the MMP-14 promoter to repress its transcription in neuroblastoma." (PMID 27259238, 2016). "Association of serum MMP-14 with clinicopathological variables in 240 gastric cancer patients." (PMID 30532247, 2018). "Notably, the immunostaining of MZF1 was associated with MMP-14 immunoreactivity in gastric cancer cases (correlation coefficient R = 0.500, P < 0.001)." (PMID 27259238, 2016). "However, the transcriptional regulators and underlying mechanisms essential for MMP-14 expression in gastric cancer are limitedly identified." (PMID 27259238, 2016). "However, the transcriptional regulators and underlying mechanisms essential for MMP-14 expression in gastric cancer still remain unclear." (PMID 28827574, 2017). "Downregulation of miR-584 in gastric cancer cells leads to increased MMP14 expression, the levels of which are directly correlated with tumorigenesis, aggressiveness of gastric cancer, and poor patient survival." (PMID 40149701, 2025). "The formation of this RNA–protein complex results in enrichment of repressive epigenetic markers at the MMP-14 promoter, decreased binding of YY1, and reduced MMP-14 transcription, thereby inhibiting the tumorigenesis and aggressiveness of gastric cancer." (PMID 38473229, 2024). "In line with the roles of miRNAs in the cell nucleus, miR-584-3p has been shown to participate in transcription regulation of the gene coding for matrix metalloproteinase 14 (MMP-14) in the nucleus of gastric cancer cells." (PMID 38473229, 2024). "In gastric cancer, miR-584-3p interacts with the promoter of MMP14 (matrix metalloproteinase 14), at an upstream region of the TSS, and represses its transcription." (PMID 38892257, 2024). "The results showed that miR-1228 can down-regulate the expression of MMP-14 and block the development of gastric cancer." (PMID 37345178, 2023). "For instance, a study using gastric cancer cells showed that YY1 directly targets the MMP-14 promoter and enhances its transcriptional activity." (PMID 37444616, 2023). "FPS reduced the tumor weight and blocked the expression of MMP-2 and MMP-14 in mice transplanted with gastric cancer, suggesting that FPS exerted anticancer effect by downregulating MMP-2 and MMP-14." (PMID 35662730, 2022). "And correlation analyses showed that MMP-14 and miR-1228 were negatively correlated in serum exocrines of patients with gastric cancer." (PMID 33883305, 2021). "In order to verify the role of miR-1228 in regulating MMP-14, we co-cultured exosomes derived from miR-1228-mimics and sh-MMP-14 transfected human BM-MSCs with gastric cancer cells." (PMID 33883305, 2021).
gastric cancer (continued). "Up-regulation of miR-1228 can down-regulate the expression of MMP-14 and effectively hinders the development and progression of gastric cancer." (PMID 33883305, 2021). "Knockdown of MMP14, regulated by miR-22, was shown to suppress the proliferation and invasion of gastric cancer cells." (PMID 34868395, 2021). "To verify the result that miR-1228 affects the growth of gastric cancer cells via regulating MMP-14, we cultured exosomes along with miR-1228-mimics+sh-MMP-14 transfected gastric cancer cells." (PMID 33883305, 2021). "The results showed that after co-culture, the effects of sh-MMP-14 on promoting proliferation, invasion, and migration of gastric cancer cells were weakened, thus accelerating apoptosis." (PMID 33883305, 2021). "In the same study it was shown that in the clinical samples, MZF1 expression correlated positively with MMP14 expression in gastric cancer." (PMID 31963147, 2020). "In gastric cancer, the expression of MMP-14 and MMP-16 was found to be upregulated, thereby promoting EMT through Wnt/β-catenin pathway." (PMID 32366234, 2020). "In this study, we confirm that survival is worse among gastric cancer patients with a high MMP14 tissue expression and, for the first time, show that survival is worse particularly when PROX1 is low." (PMID 31560170, 2019). "Five‐year disease‐specific survival for gastric cancer patients with a low MMP14 expression was 45.3% (95% CI 38.0‐52.6), whereas for patients with a high MMP14 it was 35.9% (95% CI 24.9‐46.9; P = .030)." (PMID 31560170, 2019). "This study confirms that a high MMP14 expression predicts a worse survival in gastric cancer, revealing for the first time that survival is particularly worse when PROX1 is low." (PMID 31560170, 2019). "This study, therefore, aimed to explore the association between MMP14 and PROX1 and understand their potential as prognostic biomarkers in gastric cancer." (PMID 31560170, 2019). "This further indicates that PROX1 participates in governing the MMP14 expression in gastric cancer as well." (PMID 31560170, 2019). "In conclusion, this study confirms that a high MMP14 expression predicts worse survival in gastric cancer and, for the first time, shows that survival is worse if PROX1 specifically is low." (PMID 31560170, 2019). "The aim of this study was to explore the association between matrix metalloproteinase 14 (MMP14) and prospero homeobox protein 1 (PROX1) and understand their potential as prognostic biomarkers in gastric cancer." (PMID 31560170, 2019). "Gastric cancer patients with a high MMP14 expression had a hazard ratio (HR) of 1.43 (95% CI 1.03‐1.98; P = .031) for the disease‐specific survival." (PMID 31560170, 2019). "Consistently, stable knockdown of circ-HuR increased the CNBP enrichment, promoter activity, transcripts and protein expression levels of HuR, MMP-14 and c-Myc in these gastric cancer cells, which were rescued by CRISPRi-mediated knockdown of CNBP." (PMID 31718709, 2019). "This study indicates for the first time that high serum soluble MMP-14 levels in gastric cancer serves as a marker for a poor prognosis, possibly indicating the presence of distant metastases." (PMID 30532247, 2018). "The high MMP-14 immunoexpression in 205, 225, 184, and 96 gastric cancer tissues, and in a meta-analysis of 594 patients, served as a prognostic factor and associated with age, stage, tumor grade, lymph-node metastases, distant metastases, and tumor invasion." (PMID 30532247, 2018). "Among our cohort of 240 gastric cancer patients we found that serum MMP-14 served as an independent prognostic factor." (PMID 30532247, 2018). "The MMP-14 protein and gene expression in gastric cancer tissue appear elevated in gastric cancer patients when compared to controls." (PMID 30532247, 2018). "The sensitivity of a high serum MMP-14 level to detect gastric cancer reached 16.3%, while the specificity was 70.8%." (PMID 30532247, 2018).
gastric cancer (continued). "In a large-scale study of 810 gastric cancer patients, a high MMP-14 gene expression in peripheral blood and bone marrow strongly associated with distant metastasis." (PMID 30532247, 2018). "Univariate survival analysis by subgroups, comparing a high to a low serum MMP-14 value among 240 gastric cancer patients." (PMID 30532247, 2018). "Meanwhile, the miR-584-3p expression was inversely correlated with MMP-14 transcript levels in gastric cancer tissues (R = −0.550, P < 0.001)." (PMID 28827574, 2017). "In contrast, miR-584-3p is down-regulated and negatively correlated with MMP-14 levels in clinical gastric cancer tissues, and directly targets the MMP-14 promoter to inhibit its expression." (PMID 28827574, 2017). "Nuclear run-on assay demonstrated that stable over-expression or knockdown of YY1 increased and decreased the nascent transcript levels of MMP-14 in gastric cancer cells, respectively." (PMID 28827574, 2017). "Collectively, these data suggested that miR-584-3p interacted with AGO2 to repress the YY1-facilitated MMP-14 transcription in gastric cancer cells." (PMID 28827574, 2017). "Our findings reveal the novel mechanisms of MMP-14 gene expression associated with gastric cancer progression, and suggest that YY1 and miR-584-3p are potential targets for the therapeutics of gastric cancer." (PMID 28827574, 2017). "We demonstrate, for the first time, that YY1 facilitates the expression of MMP-14 via directly binding to its promoter in gastric cancer." (PMID 28827574, 2017). "To explore the mechanisms crucial for MMP-14 expression in gastric cancer, we analyzed the potential binding sites of transcription factors within its promoter using computational algorithm programs." (PMID 28827574, 2017). "We demonstrated that YY1 directly targeted the MMP-14 promoter to facilitate its expression in gastric cancer cells." (PMID 28827574, 2017). "A positive correlation between YY1 and MMP-14 transcript levels was noted in gastric cancer tissues (correlation coefficient R = 0.625, P < 0.001)." (PMID 28827574, 2017). "miR-584-3p inhibited the in vitro and in vivo tumorigenesis and aggressiveness of gastric cancer cells through repressing YY1-facilitated MMP-14 expression." (PMID 28827574, 2017). "Our evidence indicated that YY1 expression was positively correlated with MMP-14 levels in gastric cancer specimens and cell lines." (PMID 28827574, 2017). "In summary, we have shown that YY1 is highly expressed and directly binds to the MMP-14 promoter to facilitate its transcription in gastric cancer." (PMID 28827574, 2017). "MMP-2, MMP-7, and MMP-14 are members of matrix metalloproteinase family, which play an important role in gastric cancer invasion and migration." (PMID 29358963, 2017). "We found that AGO2 was enriched surrounding the binding site of miR-584-3p within MMP-14 promoter in gastric cancer cells." (PMID 28827574, 2017). "Since above evidence indicated that miR-584-3p repressed the binding of YY1 to MMP-14 promoter, we further investigated the effects of miR-584-3p over-expression on YY1-facilitated MMP-14 levels in cultured gastric cancer cells." (PMID 28827574, 2017). "Meanwhile, ectopic expression or knockdown of MMP-14 rescued the gastric cancer cells from alteration in the viability, invasion, and angiogenesis induced by over-expression of miR-584-3p or YY1, respectively." (PMID 28827574, 2017). "The expression levels of YY1 and MMP-14 were higher in gastric cancer cell lines, when compared to those in normal gastric epithelial cells." (PMID 28827574, 2017). "Stable over-expression of YY1 resulted in enrichment of YY1 on the MMP-14 promoter in gastric cancer cells." (PMID 28827574, 2017). "Knockdown of AGO2 attenuated the transcriptional repression of MMP-14 induced by ectopic expression of miR-584-3p in gastric cancer cells." (PMID 28827574, 2017).